AR (androgen receptor)
Diseases named in the same sentence as AR in open-access papers (continued):
Sharing a sentence is not in itself a finding about the gene and the disease.
tumor (continued). "A few years ago, by recombination of prostate stromal WPMY-1 cells with PCa epithelial PC-3 cells in a mouse model, Niu and colleagues showed that stromal but not epithelial AR promotes tumor proliferation at very early stage." (PMID 25646090, 2014). "Interestingly, the inhibition of proliferation was the most pronounced in AR-positive cells and paralleled by a down regulation of PSA in the tumor xenografts." (PMID 24887556, 2014). "However, tumor recurrence within 3 years of ADT occurs in 80% of patients, and tumor regrowth combined with a rise in the AR dependent production of circulating prostate specific antigen (PSA), marks the progression to CRPC." (PMID 24722453, 2014). "The CYP17A1 up-regulation under AA is not restricted to tumour cells but is elicited when AR signaling is impaired." (PMID 25332874, 2014). "In three cases the metastasis became AR positive, whereas in 11 the metastatic lesion was negative with a concurrent AR positive primary tumor." (PMID 24505496, 2014). "Overall, superior anti-tumor activity with combination of PAN with BEZ235 was independent of AR status." (PMID 24163230, 2013). "Low doses of genistein (≤ 10μmol/L) enhanced the proliferation of PC-3 cells transfected with these tumor-derived AR mutant proteins, but not the WT- AR, and this effect was abrogated by Casodex." (PMID 24167630, 2013). "However, recent evidence has shown that DBC1 has its own role in the progression of human cancers by inhibiting the tumor suppressors BRCA1 and SUV39H1 methyltransferase, and is involved in the regulation of androgen receptor and estrogen receptor α." (PMID 24019980, 2013). "Importantly, combined targeting of PCa AR (with AR-siRNA) and anti-CCL2/CCR2 axis (with CCR2atg) notably suppressed the growth of orthotopic TRAMP-C1 tumours (siAR veh vs. siAR CCR2atg, p = 0.018)." (PMID 23982944, 2013). "Higher PA1-nuc HS levels were indicated in the groups of patients with postmenopausal group (P = 0.0097), lower tumor size (P = 0.0025), negative Ki67 (P = 0.02), and positive AR (P = 0.049) and positive ERβ (P = 0.0020)." (PMID 24260416, 2013). "PA1 nuclear expression was correlated with postmenopausal (P = 0.0097), smaller tumor size (P = 0.0025), negative Ki67 (P = 0.02), positive AR (P = 0.049) and positive ERβ (P = 0.0020)." (PMID 24260416, 2013). "High AR expression in CRPC is reproducible in some experimental models based on cell lines, cell line-based xenograft lines, and patient-derived tumor graft lines." (PMID 23896594, 2013). "Immunohistochemistry demonstrated that oestrogen receptors (ER) were negative (0%), but AR and PR were detected in 100% and 25% of tumour cells, respectively." (PMID 23816265, 2013). "It was also reported that some CRPC patient-derived tumor grafts harbor features like small cell carcinoma and do not express AR." (PMID 23896594, 2013). "Castrate-Resistant Prostate Cancer (CRPC) is characterized by persistent androgen receptor-driven tumor growth in the apparent absence of systemic androgens." (PMID 23919967, 2013). "Consistently, the expression of PIAS3 was significantly low in TRAMP-C1 siAR tumours, confirming that PIAS3 is an AR downstream target, and the PIAS3 down-regulation by AR silencing could be an important step for STAT3 activation in PCa cells." (PMID 23982944, 2013). "Androgen receptor was expressed in both the tumor and adjacent normal liver tissue with no apparent difference in protein level (data not shown)." (PMID 24080367, 2013). "The differential expression of AR according to the PTEN tumor status has not been well documented so far." (PMID 23171135, 2012). "First, there was essentially 100% negative selection against the dominant negative form of AR during castration-recurrent CWR-R1 tumor growth in the presence of supplemental T. This contrasted nearly 100% retention of the LacZ control gene." (PMID 22272301, 2012).
tumor (continued). "AR signaling can continue to stimulate tumor growth in castrate patients via intra-tumoral androgen synthesis or constitutive AR activation-independent of ligand binding." (PMID 23087897, 2012). "Intra-tumor and serum androgen levels (testosterone and DHT) in recurrent PCa appear to be sufficient to activate AR, and suggested that the PCa microenvironment may be capable of intracrine androgen biosynthesis." (PMID 22746994, 2012). "Conversely, new copy number aberrations were observed in CTCs but not in the primary tumor, including copy number gain at the AR locus." (PMID 22373240, 2012). "Disease-free survival in relation to AR diplotype groups and endocrine treatment was then estimated in patients with ER-positive tumours who had not received chemotherapy (n=436)." (PMID 22033271, 2011). "Another possible explanation for resistance to castration therapy is the presence of AR negative tumor cells, and thus AR by-pass during tumor progression." (PMID 21552559, 2011). "Although the requirement for androgen is no longer necessary in refractory disease the AR can still potentiate tumor growth and survival, thus activity of the AR remains a focal point of therapy even in advanced stages of androgen independent prostate cancer." (PMID 21539745, 2011). "MST1 serine-threonine kinase, a component of the RASSF1-LATS tumor suppressor network, binds androgen receptor (AR), but the kinase activity of MST1 is not involved in inhibition of AR." (PMID 22035226, 2011). "Methylselenocysteine consumption did not alter serum androgens; tumor proliferation rates; tumor apoptosis rates; glutathione peroxidase activity; or androgen receptor, probasin, Sep15, SepP, or SBP2 expression." (PMID 20454690, 2010). "As previously discussed, oxidative stress has also been shown to modulate AR signaling in PCa cells and hypoxia may occur as result of ADT mediated changes in tumor vascularization." (PMID 24281119, 2010). "Neoplasia observed in PB-Ack1 mice could be due to the combined effect of Ack1 mediated AKT, AR and Wwox Tyr-phosphorylations." (PMID 20333297, 2010). "As samples from all three locations were only available for six patients, this study did not allow for a meaningful analysis of AR expression related to individual tumor progression." (PMID 20565760, 2010). "Authors' response: Here we are pointing out that while AR gene amplification does occur and is not an insignificant contributor to HR tumor recurrence, such a genetic alteration does not occur in the majority of HR tumors." (PMID 20406442, 2010). "As limited data are available on the interaction between AR and Eph receptors in androgen-sensitive and independent tumours, we will not discuss this subject further in this review." (PMID 19888222, 2009). "AR does not act independently in the regulation of tumor growth but requires interaction with co-regulators." (PMID 19956729, 2009). "Because AED's central role both as a precursor of DHT and a direct activator of the androgen receptor, we initiated studies to identify an inhibitor of AED signalling in hormonally sensitive tumour cells from a proprietary chemical library based on the structure of AED." (PMID 19337256, 2009). "Most tumours from PC patients that no longer respond to endocrine therapy have retained a functional androgen receptor with often higher levels than in primary tumours." (PMID 19088719, 2009). "It should be noted that, in this study, the AR content or distribution within these tissue specimens was not assessed in any of the tumour specimens investigated." (PMID 19888222, 2009). "In accordance with other authors, we found that AR immunoreactivity is localized in the nuclei of tumor cells and no stromal staining was observed." (PMID 18507821, 2008). "The uptake of panAR-siRNA triggered a strong silencing of AR in tumor cells, prostate and testes which did not modify the blood level of testosterone." (PMID 17925854, 2007).
tumor (continued). "Specifically, cyclin D1-positive tumours were more likely to be derived from patients with lower preoperative PSA values, perhaps reflective of the established ability of cyclin D1 to modulate AR function." (PMID 17375037, 2007). "Nonetheless, we observed strong correlations between ER and many genes that have previously been shown to be strongly associated with ER positivity, including GATA3, FOXA1, AGR2, AR, and STC2, in microarray profiling studies of mixed ER-positive and ER-negative tumours." (PMID 17555561, 2007). "However, the BPA-induced cellular proliferation is dependent on AR activation, as blocking of AR function (using the specific AR antagonist, Casodex) reversed all effects of BPA on tumor cell proliferation." (PMID 18007998, 2007). "All together, these data demonstrate that the inhibition of AR signaling outside the tumor does not participate in the antitumoral effect, opening promising perspectives for developing tumor-specific treatments with reduced side effects for patients." (PMID 17925854, 2007). "The nuclear AR labeling observed in cont-siRNA treated tumor cells was no longer detected in tumors treated with AR-siRNA, where large areas of dead, TUNEL-positive cells were present." (PMID 17925854, 2007). "It is therefore highly unlikely that the inhibition of LNCaP tumor growth observed in AR-siRNA treated mice results from a non-specific mRNA degradation and apoptosis induced by interferons." (PMID 17925854, 2007). "In non-necrotic regions, mainly at the periphery of the tumor, a strong reduction in the level of AR expression and in the proportion of KI67-positive proliferating cells was observed." (PMID 17925854, 2007). "This is especially relevant as we have also identified a patient with AR amplification in the hormone-sensitive tumour, which responds fully to therapy, suggesting that AR amplification does not preclude a response to androgen deprivation therapy." (PMID 12888829, 2003). "AR expression levels in hormone-resistant tumours with and without AR amplification were not significantly different." (PMID 12888829, 2003). "CONCLUSION: AR expression is consistently detectable in GBM tissue and shows a trend toward association at the transcriptional level with non-contrast-enhancing tumor volume, suggesting a potential role in GBM biology and warranting further investigation in larger studies." (PMID 41874742, 2026). "Androgens, the main ligands of AR, have been reported to exert antiproliferative and anti-estrogenic effects in normal mammary epithelium; however, the role of AR signaling in TNBC remains controversial and appears to depend strongly on tumor molecular context." (PMID 42121935, 2026). "A 2014 study further elaborated on the AR–JUND interaction and concluded that its inhibition by pharmaceuticals like GWARJD10 can reverse the expression of SSAT and thus limit the carcinogenic impact of aberrant ROS production, thus elucidating a novel tumor preventive target." (PMID 41020863, 2025). "However, its role in TNBC remains controversial, with some studies suggesting it may contribute to tumor progression in a subset of TNBC cases, while others show limited therapeutic benefit from targeting AR in these tumors." (PMID 40734715, 2025). "Taken together these findings indicate that AR-targeted therapies may increase PI3K/AKT pathway activity by several mechanisms, with decreased ERG expression in T:E fusion tumors being a major mechanism in this tumor subset." (PMID 41321318, 2025). "Expression of PSA and AR is frequently not detected in this type of tumor." (PMID 40342821, 2025).
tumor (continued). "In patients who have progressed on ARPIs and present with a negative PSMA scan, an AR-targeted tracer such as 18F-FDHT could be used to determine if the tumor has regained AR signaling, a common resistance mechanism." (PMID 41226028, 2025). "Second, apart from the androgens produced by the adrenal glands and testis that stimulate AR, intra-tumoral secretion of enzymes involved in testosterone synthesis, such as cytochrome P450 17-alpha hydroxysteroid dehydrogenase (CYP17), also supports tumor survival and growth." (PMID 39917165, 2025). "Because tumor progression in these models involves a shift from AR-positive CRPC to AR-negative NEPC, we propose that EZH2 and PI3K/mTOR inhibitor co-treatment is particularly effective in castrate conditions due to EZH2 inhibition restoring AR expression and function." (PMID 40832297, 2025). "The phytochemical selectively upregulated tumor suppressor miRNAs, including miR-16-5p, miR-34a-5p, and miR-200a-5p in PC3 and LNCaP cells, suggesting potential involvement of pathways such as AKT3, TGF-β, and BRD4-mediated androgen receptor signaling in its mechanism of action." (PMID 41465187, 2025). "Among the 26 AR alteration‐negative patients, nine experienced tumor progression." (PMID 40558023, 2025). "The altered spectrum is associated with activation of the JAK/STAT pathway, which drives the transformation of tumor cells from an epithelial state to a mesenchymal state (EMT), a transformation that renders the tumor cells unresponsive to androgen signaling and resistant to AR inhibitors." (PMID 40017595, 2025). "Similar results were observed in intratibial and subcutaneous tumors in mice, suggesting that ECM1 may promote tumor resistance by activating AR bypass pathways rather than by reactivating the AR itself." (PMID 39563492, 2025). "Furthermore, in AR+ tumors, some SARMs can act as partial agonists or even stimulate AR activity depending on the TME, co-regulator landscape, and ligand concentration, potentially promoting tumor progression." (PMID 40940929, 2025). "Future investigations should explore potential interactions with key oncogenic pathways in PCa, such as androgen receptor signaling, PI3K/AKT/mTOR pathway, or Wnt/β-catenin signaling, which could provide deeper insights into how BAIAP2L2 influences tumor cell behavior." (PMID 40356901, 2025). "We acknowledge tumor genomic features can evolve throughout multiple lines of cancer treatment, so we subsequently limited our analysis to patients who received genetic testing within 2 years of starting 177Lu-PSMA-617, PSA50 responses were persistently lower in the AR alterations group." (PMID 41124032, 2025). "This may be because AR downstream signaling was significantly impacted by enzalutamide treatment, although enzalutamide failed to impact tumor growth by itself." (PMID 39651632, 2025). "Additionally, growth factor pathways, such as the IGF-1R and EGFR pathways, can activate AR in a ligand-independent manner, and enzymes such as CYP17A1 or AKR1C3 facilitate intratumoral androgen synthesis, providing an alternative route for tumor cells to circumvent low-androgen conditions." (PMID 40427518, 2025). "The lack of significance in 22RV1 xenograft tumor weight may reflect limitations of AR-positive cell models in immunodeficient mice." (PMID 40978029, 2025). "The tumour cells in areas with pleomorphic polygonal epithelioid type cells spread in sheets without ductal morphology showed diffuse strong immunopositivity for EMA,p63 and p40 but immunonegative for Keratin 7, AR, GCDFP-15, Her2Neu, BerEp4, S100, SMA and calponin." (PMID 40822511, 2025).
tumor (continued). "Besides AR-driven PCa, there exists an AR-indifferent subtype, in which tumor cells no longer rely on AR signaling for growth and survival." (PMID 41264145, 2025). "Similar to T877A, may allow AR to remain active in the absence of androgens, helping tumor cells escape androgen deprivation therapy." (PMID 40008000, 2025). "Despite these findings in the surgical context, modern RT trials have confirmed that androgen suppression biologically primes a tumour for radiation-induced DNA damage, while suppression of AR signalling heightens the tumour’s sensitivity to RT by blocking non-homologous DNA end-joining repair." (PMID 41514578, 2025). "Therefore, as one of the important targets of AR synthesis and a participant in AR signal transduction, PARP1 has potential in tumor treatment and may provide an effective treatment strategy for mCRPC and mRCC patients." (PMID 38965120, 2024). "However, further work must prove AR’s role in the observed DSRCT cell and tumor growth reductions." (PMID 38575753, 2024). "CU-PC01 tumours display DNPC-like clinicopathological features, including the absence of AR, PSA and PSMA, loss of PTEN and RB, and a lack of NE markers, including SYP, neuronal differentiation 1 (NEUROD1), POU class 2 homeobox 3 (POU2F3) and achaete-scute homolog 1 (ASCL1)." (PMID 38667288, 2024). "In summary, by interfering with the AR/FlnA complex, targeting several extracts, and inhibiting the activity of key factors, such as YAP1, CXCL12, and TGF-β, the pro-tumor function and ability to maintain the CAF tumor can be effectively impaired, providing a new approach for PCa treatment." (PMID 39092186, 2024). "However, unlike ERα, which promotes BC tumor growth, the functions and roles of AR and AR modulators in BC are controversial." (PMID 38965614, 2024). "Additionally, activation of bypass signaling pathways, such as the glucocorticoid receptor (GR) and neuroendocrine differentiation (NED), can sustain tumor growth independent of AR signaling." (PMID 39184676, 2024). "Of note, the AR+ HOXB13–negative GRN in the ARhigh/PSMAlow sample showed robust STEAP1 and STEAP2 expression, suggesting that co–targeting of STEAP and PSMA in AR–positive disease may be an effective strategy to achieve broader tumor cell coverage." (PMID 38645034, 2024). "This interaction may play a role in mediating the tumor suppressor activity of AR in breast tissues regardless of ER status." (PMID 38317241, 2024). "It is possible that Lathyrol may influence the expression of CYP17A1 and PARP1, thereby affecting the synthesis and phosphorylation of AR, then produce negative results to the function and activity of neoplasm cells." (PMID 38965120, 2024). "AR expression was absent in tumor cells at both metastatic sites." (PMID 39394434, 2024). "Moreover, it mitigated metastasis and elicited tumor suppressive effects in AR-negative and castration-resistant prostate cancer (CRPC)." (PMID 39175529, 2024). "In our study, AR expression did not correlate with tumor size." (PMID 39497884, 2024). "Interestingly, JunD and β-catenin were necessary for menin’s tumor-suppressive activity in AR-negative cell lines, as knocking down JunD or β-catenin abolished the increased colony formation observed with menin knockdown." (PMID 39336822, 2024). "TMPRSS2:ERG is an AR regulatory gene that is restored in CRPC and may promote tumor progression." (PMID 38887275, 2024). "There is a possibility that the forced overexpression of AR in TNBC may result in AR acting like a tumor suppressor rather than behaving as an oncogenic driver, which occurs when it is endogenously expressed." (PMID 38339092, 2024). "Also, it has been studied that AR is expressed in 32% of TNBC cases and it may be involved in tumor development." (PMID 38338747, 2024). "Once progressed, tumor cells no longer express AR as a mechanism of resistance to previous ADT." (PMID 38903357, 2024).